KIF4A (kinesin family member 4A)
Diseases named in the same sentence as KIF4A in open-access papers (continued):
Sharing a sentence is not in itself a finding about the gene and the disease.
glioma (continued). "Subsequently, the GEO (GSE4290, GSE50161) and TCGA databases were used to analyze the expression of KIF4A in glioma, and the results showed that KIF4A was significantly overexpressed in glioma." (PMID 38937742, 2024). "WZ-3146, a small molecule inhibitor of KIF4A, can inhibit glioma growth and induce glioma cell apoptosis, thus exerting antiglioma effects." (PMID 38937742, 2024). "Kaplan‒Meier survival analysis demonstrated that glioma patients with high KIF4A expression had shorter survival times than patients with low KIF4A expression." (PMID 38937742, 2024). "Futher, the TCGA and CGGA database were utilized to explore the correlation of KIF4A expression with glioma prognosis." (PMID 38937742, 2024). "Our analysis revealed that the expression of KIF4A was significantly decreased in glioma patients with 1p19q codeletion and that KIF4A was significantly upregulated in patients with recurrent glioma." (PMID 38937742, 2024). "Given that KIF4A overexpression is related to glioma prognosis, we further evaluated the feasibility of targeting KIF4A for glioma treatment." (PMID 38937742, 2024). "First, genes coexpressed with KIF4A in glioma patients in the TCGA database were screened by Pearson correlation analysis." (PMID 38937742, 2024). "Then, qRT-PCR and Western blot was used to detect the KIF4A mRNA and protein expression level in glioma cells, respectively." (PMID 38937742, 2024). "Subsequently, the effect of KIF4A knockdown or WZ-3146 treatment on glioma was measured by the MTT, EdU, Colony formation assay and Transwell assay." (PMID 38937742, 2024). "A colony formation assay was subsequently performed to further determine the inhibitory effect of siKIF4A on glioma cell proliferation, and we found that the number of colonies formed was reduced by KIF4A inhibition in glioma cells." (PMID 38937742, 2024). "Next, univariate and multivariate Cox regression analysis were carried out to confirm the feasibility of KIF4A as an independent prognostic factor for glioma." (PMID 38937742, 2024). "Univariate Cox regression analysis indicated that KIF4A expression was negatively related to glioma prognosis in the TCGA database (HR = 1.870, P < 0.001), and similar results were obtained in the CGGA database (HR = 1.777, P < 0.001)." (PMID 38937742, 2024). "Taken together, these results suggest that overexpression of KIF4A is significantly correlated with poor prognosis in glioma patients." (PMID 38937742, 2024). "Because KIF4A overexpression is associated with poor prognosis in glioma patients, we aimed to demonstrate the effect of KIF4A knockdown on glioma treatment." (PMID 38937742, 2024). "Taken together, these observations reveal that WZ-3146 is highly likely to induce glioma cell apoptosis via KIF4A inhibition." (PMID 38937742, 2024). "We also discovered that WZ-3146, a small molecule inhibitor of KIF4A, can induce apoptosis in glioma cells and exhibit antiglioma effects." (PMID 38937742, 2024). "Overall, these results supported the idea that high KIF4A expression is an independent factor indicating poor prognosis in glioma." (PMID 38937742, 2024). "The results confirmed that KIF4A knockdown significantly reduced glioma cell viability and proliferation." (PMID 38937742, 2024). "And the western blot results confirmed that the KIF4A expression in gliomas also showed a dose- and time-dependent on WZ-3146 treatment." (PMID 38937742, 2024). "Reports have demonstrated that glioma patients with wild-type IDH have a worse prognosis than those with IDH mutation, and our results confirmed that KIF4A overexpression in patients with wild-type IDH was greater than that in patients with IDH mutation." (PMID 38937742, 2024). "Our subsequent results demonstrated that WZ-3146 inhibit KIF4A expression in glioma and decreased glioma cell viability and proliferation." (PMID 38937742, 2024).
glioma (continued). "Subsequent studies revealed that WZ-3146 can act as a small molecule inhibitor of KIF4A to inhibit glioma cell growth and induce glioma cell apoptosis, ultimately demonstrating a good inhibitory effect on glioma progression." (PMID 38937742, 2024). "Consistently, with the increase in risk score, the expression of KIF4A and KIF13B, as well as the mortality rate of glioma patients, increased remarkably." (PMID 36837615, 2023). "To verify the function of KIF4A in glioma cells in CSC and EMT, we additionally performed the experiments using siRNA treated U373 cells, and observed that KIF4A regulates CSC and EMT properties not only in U87 cells but also in U373 cells." (PMID 38067227, 2023). "We crucially identified that KIF4A drives gliomas growth by transcriptional repression of Rac1/Cdc42 to induce cytoskeletal remodeling in glioma cells." (PMID 36606197, 2022). "In this study, considering the carcinogenicity of KIF4A in certain human tumors, we investigate the potential connection related to glioma." (PMID 36606197, 2022). "We refined the observation time point to further observed the effect of KIF4A on the morphological progression of glioma cells in each one hour, and obtained the same conclusion." (PMID 36606197, 2022). "Our work is the initial demonstration of KIF4A biologic function correlated with malignant progress of glioma cells." (PMID 36606197, 2022). "Western blot also showed that KIF4A was overexpressed in glioma tissue samples (T) compared with the adjacent normal brain tissues (N)." (PMID 36606197, 2022). "Chromatin Immunoprecipitation (ChIP) analysis was applied to searching potential KIF4A related downstream in glioma." (PMID 36606197, 2022). "Further, KIF4A protein expressions were evaluated in normal human astrocyte cell (NHA) and several glioma cells, the western blot assays revealed that KIF4A protein levels were upregulated in glioma cells compared with that in NHA cell." (PMID 36606197, 2022). "In conclusion, our study shows in the first time that aberrant expression of KIF4A contributes to the proliferation and cytoskeletal remodeling progression of glioma cells." (PMID 36606197, 2022). "We analyzed the KIF4A expression and the prognosis in gliomas patients using The Cancer Genome Atlas (TCGA) databases." (PMID 36606197, 2022). "We studied the function of KIF4A on proliferation, migration, invasion, cell cycle in glioma cell lines using a series of in vitro and in vivo experiments." (PMID 36606197, 2022). "KIF4A, 9, 18A, and 23 genes showed that, as the degree of glioma increased, the degree of staining also increased." (PMID 30872592, 2019). "Particularly, esophageal carcinoma, breast invasive carcinoma, kidney renal clear cell carcinoma, low grade gliomas showed larger difference on overall survival between high and low levels of KIF4A expression." (PMID 28646197, 2017). "Because KIF4A may be a good target for glioma treatment, we utilized the CMap online database to predict inhibitors of KIF4A, and WZ-3146 was ultimately identified as a potential small molecule inhibitor of KIF4A." (PMID 38937742, 2024). "Ultimately, GSEA enrichment analysis was performed to find that the apoptotic pathway could be regulated by KIF4A in glioma, in addition, the effect of WZ-3146 on glioma apoptosis was detected by flow cytometry and Western blot." (PMID 38937742, 2024). "In the present study, we confirmed that KIF4A is abnormally overexpressed in glioma." (PMID 38937742, 2024). "KIF4A expression was positively correlated with glioma grade." (PMID 38937742, 2024). "Therefore, we further examined the effect of WZ-3146 on glioma cell apoptosis, and the results confirmed that WZ-3146 can significantly induce glioma cell apoptosis, which further confirmed that WZ-3146 can limit glioma progression by targeting KIF4A." (PMID 38937742, 2024). "In conclusion, these observations demonstrated that targeting KIF4A can inhibit glioma progression." (PMID 38937742, 2024).
glioma (continued). "We then explored whether the inhibitory effect of WZ-3146 on glioma was mediated through the inhibition of KIF4A expression." (PMID 38937742, 2024). "We speculate that WZ-3146 may be a novel drug targeting KIF4A that could be use in combination with other targeted drugs, which may be an effective chemotherapeutic strategy for glioma." (PMID 38937742, 2024). "Collectively, these evidences indicate that KIF4A has different functions in different tumors; however, the association of KIF4A expression with glioma has not been comprehensively revealed." (PMID 38937742, 2024). "In addition, KIF4A overexpression is a key indicator of glioma prognosis; moreover, suppressing KIF4A expression can inhibit glioma progression." (PMID 38937742, 2024). "This indirect evidence preliminarily proves that WZ-3146 may suppress EGFR expression, ultimately inhibiting KIF4A expression, in glioma." (PMID 38937742, 2024). "Finally, KIF4A expression was found to have the strongest correlations with the clinical characteristics of glioma patients, and KIF4A was eventually selected as the object for subsequent research." (PMID 38937742, 2024). "The apoptosis signaling pathway was positively correlated with KIF4A expression in glioma." (PMID 38937742, 2024). "Overall, we believe that through future in-depth research, WZ-3146 may be used for adjuvant chemotherapy for glioma.Meanwhile, we have only demonstrated that WZ-3146 could suppress glioma progression by inhibiting KIF4A expression in vitro." (PMID 38937742, 2024). "With further research, WZ-3146, a small molecule inhibitor of KIF4A, could be combined with other molecular targeted drugs to cooperatively inhibit glioma progression." (PMID 38937742, 2024). "Moreover, KIF4A overexpression reversed the inhibitory effect of WZ-3146 on glioma cell activity, suggesting that WZ-3146 can inhibit glioma progression by inhibiting KIF4A expression." (PMID 38937742, 2024). "Subsequently, we conducted experiments to elucidate the function of KIF4A in glioma stem cells." (PMID 38067227, 2023). "We also investigated the expression of PAI-1, a gene regulated by KIF4A, in a glioma cell line." (PMID 38067227, 2023). "Knockdown KIF4A decreased glioma cell proliferation and metastasis." (PMID 36606197, 2022). "We identified the significant up-regulated expression of KIF4A both in glioma tissues and cell." (PMID 36606197, 2022). "Glioma patients with elevated KIF4A expression have shorter survival." (PMID 36606197, 2022). "Survival analysis of TCGA datasets revealed that high KIF4A expression was significantly correlated with poor cumulative survival (p < 0.01), and high KIF4A expression in different grade glioma showed poor survival compared with low KIF4A expression (p < 0.01)." (PMID 36606197, 2022). "The effects of KIF4A on the proliferation of glioma cells were validated in a xenograft mouse model injected with the same number of SH or NC glioma cells in situ implantation in the brain of nude mice, and data showed that knockdown of KIF4A inhibited glioma cells growth." (PMID 36606197, 2022). "Our study provided a prospect that KIF4A functions as an oncogene in glioma." (PMID 36606197, 2022). "This study aimed to explore the potential function and mechanism of KIF4A in gliomas." (PMID 36606197, 2022). "Colony formation assays also suggested that KIF4A knockdown could effectively repress glioma cells growth." (PMID 36606197, 2022). "It suggested that silencing KIF4A may induce cytoskeletal remodeling to regulate glioma cell mobility." (PMID 36606197, 2022). "Flow cytometry assays showed that knockdown KIF4A inhibited cell cycle in glioma cells." (PMID 36606197, 2022). "To precisely unravel the pathways that were related to the function of KIF4A in cytoskeletal remodeling of glioma, we hypnosis that whether KIF4A regulated F-actin through RhoA or Rac1/Cdc42." (PMID 36606197, 2022). "We showed that KIF4A is highly expressed in glioma and indicated poor prognosis." (PMID 36606197, 2022).
glioma (continued). "We also showed that KIF4A promotes glioma cells growth in vitro and in vivo." (PMID 36606197, 2022). "We queried the expression of KIF4A in TCGA database and found that it is enriched in glioma." (PMID 36606197, 2022). "It revealed a positive role of KIF4A in promoting cell migration and invasion in glioma cells." (PMID 36606197, 2022). "Above, we demonstrated that WZ-3146 could inhibit glioma progression via KIF4A inhibition." (PMID 38937742, 2024). "However, the mechanism by which WZ-3146 acts as an EGFR inhibitor to inhibit KIF4A expression in glioma remains unclear." (PMID 38937742, 2024). "Next, MTT assays suggested that KIF4A overexpression reversed the inhibitory effect of WZ-3146 on proliferation in U251 glioma cell line, moreover, the western blot results confirmed that the KIF4A over-expression could reverse the effect of WZ-3146 on KIF4A protein expression in glioma." (PMID 38937742, 2024). "In addition, these results provide preliminary confirmation that targeting KIF4A may constitute a therapeutic approach for glioma." (PMID 38937742, 2024). "However, little is known about the correlation between KIF4A and gliomas." (PMID 36606197, 2022). "However, the association between KIF4A expression and glioma have not been reported, and the role of KIF4A in glioma was never investigated." (PMID 36606197, 2022). "Thus, we investigated the role of KIF4A in glioma migration and invasion by transwell assays." (PMID 36606197, 2022). "However, the mechanism of KIF4A on glioma is yet to be investigated." (PMID 36606197, 2022). "It suggested KIF4A may regulate glioma cells growth and mobility through the Rac1/Cdc42 pathway." (PMID 36606197, 2022). "The AUCs of the ROC curves for predicting the 1-year, 3-year, and 5-year survival outcomes of glioma patients in the TCGA and CGGA databases were all greater than or close to 0.7, suggesting that KIF4A expression can be used to predict glioma patient survival." (PMID 38937742, 2024). "Moreover, targeting KIF4A could significantly suppress the progression of glioma." (PMID 38937742, 2024). "Considering that KIF4A expression is related to glioma prognosis, gene set enrichment analysis (GSEA) was used to identify the pathways possibly affected by KIF4A." (PMID 38937742, 2024). "Therefore, we speculated that WZ-3146 can inhibit glioma progression by downregulating KIF4A." (PMID 38937742, 2024). "KIF4A level in normal human astrocyte cell (NHA) and glioma cell lines were examined by Western blot." (PMID 36606197, 2022). "Consistently, circKIF4A had a long half-life time compared to the linear KIF4A mRNA due to the circular form in SHG-44 and A172 glioma cell lines." (PMID 36030248, 2022). "We found that the expression of KIF4A and BRCA1 was significantly correlated with each other in glioma (R = 0.76 and p-value < 0.001), providing a functional link between RBP and gene." (PMID 32047515, 2019). "AS of KIF4A and AS of FKBP11 were hub events in this network with important splicing predictors of glioma prognosis." (PMID 31729991, 2019). "Here, we confirmed that KIF4A expression is significantly elevated in glioma and negatively correlated with the prognosis of glioma patients by analyses of the TCGA, CGGA, and GEO (GSE4290, GSE50161) databases." (PMID 38937742, 2024). "Recent research demonstrated that KIF4A knock-down can suppress the glioma stem cells marker expression including CD133, ALDH1A1, and ALDH1A3, meanwhile, KIF4A over-expression can promote the epithelial-to-mesenchymal transition (EMT) of glioma." (PMID 38937742, 2024). "We treated U87 cells, a glioma cell line, with sphere-forming media and observed that the expression of CSC marker proteins, including CD133, ALDH1A1, and ALDH1A3, was diminished in the group where KIF4A expression was knocked down." (PMID 38067227, 2023).
glioma (continued). "After WZ-3146 treatment of glioma cell lines (U251 and LN229), KIF4A mRNA and protein expression in these cells was measured by qRT‒PCR and Western blot analyses, and the results demonstrated that KIFA4 expression was strongly decreased by WZ-3146 treatment in glioma cell lines (U251 and LN229)." (PMID 38937742, 2024). "However, the specific molecular mechanism by which WZ-3146 inhibits KIF4A expression in glioma is not clear and is the focus of our next study." (PMID 38937742, 2024). "However, the expression and function of KIF4A in glioma cells have never been investigated." (PMID 36606197, 2022).
gastric cancer (10 papers, 2013 to 2024). A primary or metastatic malignant neoplasm involving the stomach. "Because KIF4A silencing reduces p‐AKT level in gastric cancer, we investigated the effect of KIF4A silencing on AKT activation and the protein level of downstream apoptosis‐related genes in UBC cells." (PMID 37039264, 2023). "In contrast, KIF4A was downregulated in gastric cancer, and its elevation inhibits the proliferation of human gastric carcinoma cells." (PMID 36499051, 2022). "Kif4A is also downregulated in gastric carcinoma tissues and Kif4A expression levels correlate with tumor differentiation." (PMID 28218637, 2017). "In addition, KIF4A overexpression can promote endometrial cancer progression by inhibiting TPX2 protein degradation, while KIF4A expression is reduced in gastric cancer, multiple myeloma, and acute myeloid leukemia." (PMID 38937742, 2024). "A recent study has shown that KIF4A silencing reduces p‐AKT level in gastric cancer." (PMID 37039264, 2023).
osteosarcoma (9 papers, 2021 to 2025). A usually aggressive malignant bone-forming mesenchymal neoplasm, predominantly affecting adolescents and young adults. "Conversely, the downregulation of KIF4A can suppress colony formation, invasion, migration, and disrupt the cell cycle of osteosarcoma cells." (PMID 40600015, 2025). "Increased expression of KIF4A was indicative of a poor prognosis and contributes to tumor growth in osteosarcoma." (PMID 40600015, 2025). "The expression of DEPDC1 and KIF4A in osteosarcoma tissues and the correlation of them will be investigated in future study." (PMID 36849972, 2023). "The results showed that the level of mRNA and protein of KIF4A in osteosarcoma cell lines were significantly higher than those of normal osteoblasts hFOB1.19." (PMID 34055488, 2021). "We determined KIF4A mRNA and protein expression in osteosarcoma (OS) cells." (PMID 34055488, 2021). "In osteosarcoma, the DEPDC1/KIF4A axis promotes malignant behaviours and EMT by inhibiting the Hippo pathway, resulting in decreased p-LATS1/p-YAP levels." (PMID 41361459, 2025). "Exo-miR-150 targets IGF2BP1, Exo-miR-195 targets KIF4A, Exo-miR-206 targets NRSN2, and RGD-Exo targets Rad18, along with other pathways that impede the evolution of osteosarcoma." (PMID 39605980, 2024).